IMMP1L (inner mitochondrial membrane peptidase subunit 1)
Description:
Catalyzes the removal of transit peptides required for the targeting of proteins from the mitochondrial matrix, across the inner membrane, into the inter-membrane space. Known to process the nuclear encoded protein DIABLO.
Synonyms: FLJ25059; IMMP1; IMP1; IMP1-LIKE
Tractability: No criterion of Open Targets' tractability assessment is met for any kind of drug.
Gene: Protein-coding gene on chromosome 11 (31,432,399 to 31,509,645, reverse strand). Ensembl gene ENSG00000148950.
Subcellular location: Mitochondrion inner membrane
Subcellular location (Human Protein Atlas): Mitochondria
Gene Ontology:
Molecular function: endopeptidase activity; serine-type endopeptidase activity; serine-type peptidase activity
Biological process: protein processing; proteolysis
Cellular component: mitochondrion; mitochondrial inner membrane; mitochondrial inner membrane peptidase complex; membrane
Genetic constraint (gnomAD): Loss-of-function variants: 1 observed, 1.82 expected, observed/expected ratio (o/e) 0.55, 90% interval 0.18 to 1.78. That is too few expected variants to judge how well the gene tolerates losing a copy. Missense variants: 27 observed, 25.81 expected, observed/expected ratio (o/e) 1.05, 90% interval 0.77 to 1.44. Synonymous variants: 7 observed, 9.42 expected, observed/expected ratio (o/e) 0.74, 90% interval 0.42 to 1.39.
Homologues: Orthologues: chimpanzee IMMP1L (100% identical), macaque IMMP1L (99% identical), dog IMMP1L (97% identical), mouse Immp1l (94% identical), rabbit IMMP1L (88% identical), pig IMMP1L (84% identical), rat Immp1l (81% identical), guinea pig IMMP1L (75% identical), zebrafish immp1l (70% identical), tropical clawed frog immp1l (52% identical), Drosophila melanogaster CG9240 (45% identical), Caenorhabditis elegans immp-1 (37% identical). Paralogues in human: IMMP2L (31% identical).
Diseases named in the same sentence as IMMP1L in open-access papers:
IMMP1L is named in the same sentence as 5 diseases in open-access papers, as found by Europe PMC text mining. Sharing a sentence is not in itself a finding about the gene and the disease. The quoted sentences say what the papers report.
aniridia (3 papers, 2011 to 2023). Aniridia is a congenital ocular malformation characterized by the complete or partial absence of the iris. "In this study, the novel 517 kb heterozygous deletion (chr11:31,139,019–31,655,997) downstream of PAX6 containing four annotated genes, DCDC1, DNAJC24, IMMP1L, and ELP4, is likely to be the cause of the familial aniridia in this Chinese family." (PMID 37752489, 2023). "Taken together, a 517 kb heterozygous deletion containing four annotated genes, DCDC1, DNAJC24, IMMP1L, and ELP4, was identified in this Chinese family with congenital aniridia, suggesting that transcription-regulating elements in the deleted region are required for the expression of PAX6." (PMID 37752489, 2023). "Recently a ~406 kb heterozygous genomic deletion containing four annotated genes (DCDC1, DNAJC24, IMMP1L, and ELP4) was found in patients with aniridia; apparently the gene contents in this deletion are the same as the 566 kb heterozygous deletion in the family we report here." (PMID 21321669, 2011).
cervical cancer (1 paper, 2021). A primary or metastatic malignant neoplasm involving the cervix. "The remaining 10 genes (i.e., YJEFN3, SPATA5L1, C5orf55, PPM1A, IMMP1L, ZNF330, PPIP5K2, ESCO2, FICD, and ZNF225) are not directly reported to be related to the survival risk of cervical cancer in previous literature." (PMID 34149809, 2021).
IMMP1L also shares sentences with these, for which no sentence is quoted: atherosclerosis (1 paper); autism (1); Obesity (1).